SLAMF7 (SLAM family member 7)
Diseases named in the same sentence as SLAMF7 in open-access papers (continued):
Sharing a sentence is not in itself a finding about the gene and the disease.
tumor (97 papers, 2013 to 2026). "Phagocytosis and elimination of hematopoietic tumor cells by macrophages require SLAMF7 independently of SLAM-associated adaptors." (PMID 40231463, 2025). "The “eat me” signals mainly include tumor-associated antigens generated in response to oncogenic stresses, the ER chaperone protein calreticulin and the glycoprotein SLAMF7." (PMID 36882399, 2023). "Of note, several tumor-associated exhaustion markers were expressed on a larger proportion of SLAMF7+CD8+ T cells compared to SLAMF7−CD8+ T cells." (PMID 33597728, 2021). "In contrast to CD28 signaling, SLAMF7 engagement reduced IL-10 secretion, a cytokine with well-established immunosuppressive functions, as well as IL-6 levels, which has been implicated in inflammation-driven tumor progression." (PMID 40909279, 2025). "Moreover, sequential SLAMF7 engagement followed by ICB improves T-cell responses against the tumor-associated self-antigen NY-ESO-1." (PMID 40909279, 2025). "However, these same properties increase the risk of on-target/off-tumor toxicity against normal SLAMF7+ cells." (PMID 41228264, 2025). "These tumor types may be particularly susceptible to SLAMF7-based immunotherapies." (PMID 41168829, 2025). "Coculture with SLAMF7-overexpressing CT26 tumor cells significantly increased CD107a (Lysosomal-associated membrane protein 1, LAMP1) surface expression on DNT, a maker of degranulation, compared to control CT26 cells, indicating that SLAMF7 ligation could promote DNT cell degranulation." (PMID 41168829, 2025). "Besides, tumor-associated glycoforms of conventional antigens, including SLAMF7, CLEC14A, PDPN, PODXL, and CD44, could also be ideal target antigens." (PMID 36261831, 2022). "A suicide gene within the SLAMF7 CAR-T encodes a dimerization domain containing a caspase-9 domain, which is efficacious in the high-tumor-burden myeloma model, despite the fratricide of CD8+CS1-expressing CAR-T cells." (PMID 41228264, 2025). "Given the observed SLAMF7-dependent antitumor effects, we next evaluated SLAMF7 expression in paired tumor and adjacent normal tissues based on TCGA’s database to explore the translational potential of SLAMF7+ DNT therapy." (PMID 41168829, 2025). "For the purpose of comparing activation of either single or dual CARtein cells when co-cultured with cells expressing BCMA, SLAMF7 or both tumor antigens, we performed a Two-way ANOVA analysis." (PMID 40821776, 2025). "SLAMF7 is expressed exclusively on the surface of hematologic tumor cells, which promotes tumor cells phagocytosis by binding with its equal receptor SLAMF7 on phagocytes." (PMID 40835598, 2025). "To further explore the relationship between DNT functional molecules and SLAMF7 expression in the tumor microenvironment (TME), we analyzed DNT infiltrating tumors in an implanted A20 tumor model." (PMID 41168829, 2025). "Compared to SLAMF7− DNT, adoptively transferred SLAMF7+ DNT had an increased tumor-infiltrating level, elevated Ki67 expression, and significantly elevated production of cytotoxic molecules, such as granzyme A, granzyme B and perforin." (PMID 41168829, 2025). "After tumor establishment, either SLAMF7− or SLAMF7+ DNT from C57BL/6 mice were administered peritumorally after in vitro activation." (PMID 41168829, 2025). "SLAMF7 has been reported to promote the induction and activation of NK cell cytotoxicity, and enhance macrophage-mediated phagocytosis of tumor cells, recognized as a critical immunoregulatory receptor involved in antitumor immunity." (PMID 41168829, 2025). "The vehicle-treated xenografts also showed higher Pd-l1 expression and more restricted Slamf7 expression in non-tumor regions compared with the ST-5-002–treated xenografts." (PMID 39828766, 2025). "SLAMF7-SLAMF7 interactions between macrophages and tumor cells are required for tumor cell phagocytosis." (PMID 41168829, 2025).
tumor (continued). "PSMB9 displayed strong correlations with classical inhibitory molecules such as LAG3, PDCD1, CTLA4, TIGIT, HAVCR2, SLAMF7, and PD-L1 across nearly all tumor types." (PMID 41020834, 2025). "To better elucidate the role of SLAMF7 in DNT-mediated tumor killing via homotypic ligand-receptor interaction, we performed in vitro co-culture experiments and employed an anti-SLAMF7 antibody acting as receptor agonists to mimic ligand engagement." (PMID 41168829, 2025). "Although differential expression was observed in a limited number of tumor types, these findings supported the potential of SLAMF7 expression as a predictive biomarker to identify patients most likely to benefit from SLAMF7+ DNT therapy." (PMID 41168829, 2025). "Previous studies reported that SLAMF7 is thought to engage in homotypic interactions with its own ligand to mediate tumor cell killing." (PMID 41168829, 2025). "The next important step is to identify these TCR/SLAMF7-mediated adaptor–kinase combinations that are active in effector, memory and tumor-infiltrating CD8+ T-cell subsets." (PMID 40909279, 2025). "Due to its high expression on myeloma cells monoclonal antibodies have been developed to target SLAMF7 as a tumor antigen, leading to NK-cell mediated antibody-dependent cellular cytotoxicity (ADCC)." (PMID 40909279, 2025). "This further underlines the potential of SLAMF7 to restore T-cell function in the tumor environment and makes SLAMF7 an interesting agonistic target for immunotherapeutic approaches in solid tumors." (PMID 40909279, 2025). "Among them, 2B4 (CD244) and CS1 (SLAMF7) are major NK cell receptors playing a significant role in anti-tumor immunity." (PMID 40852706, 2025). "Within this cluster of the tumor cells, there is a SLAMF7-positive macrophage indicated by the red arrow." (PMID 38920727, 2024). "This mouse trial demonstrated the efficacy of SLAMF7 CAR-T cells in mediating potent anti-tumor effects." (PMID 39234257, 2024). "We also investigated the impact of previous therapy and tumor characteristics, such as cell surface expression of SLAMF7, on the ex vivo efficacy of UCARTCS1." (PMID 39060023, 2024). "Researchers demonstrated the in vitro expression of SLAMF7 with suicide gene-specific CAR in T cells, as well as the specific recognition and eradication of SLAMF7-positive cells in mice tumor models." (PMID 39220130, 2024). "We first examined the relationship between tumor SLAMF7 expression levels and UCARTCS1-mediated lysis in 25 out of 29 patients from whom enough BM material was collected." (PMID 39060023, 2024). "It was demonstrated that SLAMF7 is indispensable in CD47 blockade-induced tumor cell phagocytosis, and this function of SLAMF7 relies on the interaction between SLAMF7 and integrin Mac-1." (PMID 37754488, 2023). "As a surface receptor with broad expression on immune cells and MM tumor cells, SLAMF7 is gradually becoming a promising checkpoint in tumor immunotherapy." (PMID 36749634, 2023). "These single cell transcriptome analyses confirmed the induction of CD274 overexpression by cyclophophamide in the 4T1 tumor immune microenvironment, especially in B cells, in Monocyte/Macrophage Lyz2+ or Skfn4+ and in dendritic cells of Slamf7+." (PMID 38201582, 2023). "SLAMF7 (signaling lymphocytic activation molecule family 7, also known as CRACC, CS1, and CD319) remarkably facilitates engulfment of a few hematopoietic tumor cells expressing SLAMF7 such as Raji during CD47-SIRPα blockade." (PMID 36081498, 2022). "A deeper characterization of these population in various human cancers have shown the involvement of SLAM family member 7 (SLAMF7) gene expression as a direct regulator of tumor-specific CD4+ T cell cytotoxicity." (PMID 35008422, 2022). "Another in vitro study of CAR-NK cells targeting SLAMF7 cell therapy demonstrated an enhanced interferon-gamma production and cytotoxic activity against primary MM tumor cells, as well as inhibition of MM tumor growth in a xenograft mouse model." (PMID 35877215, 2022).
tumor (continued). "The MAbs targeting SLAMF7 such as elotuzumab are able to activate NK cells and enhance antibody-dependent cell-mediated cytotoxicity, making SLAMF7 an attractive target in tumour immunotherapy." (PMID 34488679, 2021). "CAR-NK 92 cells targeting SLAMF7 not only showed intensified in vitro cytolysis, but also anti-tumor activity in murine tumor models and prolonged mouse survival." (PMID 32943087, 2020). "To investigate if tumor-expressed SLAMF7 was a requisite for phagocytosis of DLBCL cells upon CD47 targeting, we generated type 1 macrophages (MØ) as the prototype pro-inflammatory macrophage subtype associated with anti-cancer activity." (PMID 30710089, 2019). "Even more interestingly, SLAMF7 has been recently revealed to be critical in phagocytosis mediating macrophages engulf and destroy haematopoietic tumor cells." (PMID 29905534, 2018). "To explore whether SLAMF7+ DNT modulate the tumor immune microenvironment, we profiled tumor-infiltrating innate immune populations in BALB/c nude mice." (PMID 41168829, 2025). "As for the off-tumor toxicity risks for CARtein constructs targeting SLAMF7 and BCMA, they are expected to be identical to conventional CAR-T therapies using the same humanized scFvs, as the mature CARtein receptor is structurally equivalent except for a 6-amino acid scar." (PMID 40821776, 2025). "In the current study, we demonstrated that SLAMF7 ligation with ligands of tumor cells or clinical-grade monoclonal antibody elotuzumab could enhance antitumor cytotoxicity in DNT by promoting cell degranulation." (PMID 41168829, 2025). "Since we figured out that SLAMF7 engagement enhances T-cell responses against the tumor antigen NY-ESO-1 in healthy donors, we wanted to investigate whether this effect is preserved in cancer patients." (PMID 40909279, 2025). "We found that compared with NK92-EV cells, NK92-TM4SF5 cells caused more aggressive tumor formation, although Slamf7 immunostaining in the xenografted tumors was not clearly different between the two NK92 cell lines." (PMID 39828766, 2025). "Furthermore, the tumor lesions from DEN-treated TG mice showed weaker Slamf7 and Nkg2d immunostaining and stronger Tigit and nuclear Ki67 staining compared with non-tumor areas, although TM4SF5 staining was comparable between tumor and non-tumor regions." (PMID 39828766, 2025). "Decreased SLAMF7 expression on A20 cells impaired the tumor-killing activity of DNT." (PMID 41168829, 2025). "However, the liver tissues of a patient with insignificantly changed TM4SF5 expression (i.e., TM4SF5-independent) showed less SLAMF7 in the LAMP1 immunoprecipitates from tumor tissue compared with that from non-tumor tissue (lanes 1 to 2)." (PMID 39828766, 2025). "This includes investigating whether mPCs downregulate SLAMF7 expression or develop alternative escape mechanisms, and how the tumour influences these processes." (PMID 41228264, 2025). "Furthermore, SLAMF7 expression has been observed on specific immune cells, which has the potential to result in on-target, off-tumour toxicity." (PMID 41228264, 2025). "Additionally, Flow cytometric analysis revealed that SLAMF7+ DNT induced a higher level of tumor cell apoptosis than SLAMF7− DNT." (PMID 41168829, 2025). "SLAMF7 could be identified to enhance CD8+ T-cell responses against infectious but also tumor antigens." (PMID 40909279, 2025). "Additionally, SLAMF7 expression on tumor targets has been reported to enhance NK cell-mediated cytotoxicity via SLAMF7 ligation-induced degranulation." (PMID 41168829, 2025). "In samples with high expression, up to 70% of tumor cells expressed high levels of SLAMF7." (PMID 38476238, 2024). "In vitro studies showed that agonistic engagement of SLAMF7 on tumor-specific CD4+ T-cells enhanced their cytolytic activity, which, if expressed by CD4+ T-cells in these tumors, may explain the relationship with favorable prognosis." (PMID 38476238, 2024).
tumor (continued). "T cells expressing Bi-ChTCRs targeting CD19 and CD22 or BCMA and SLAMF7 recognized target cells expressing either one or both target proteins and exhibited superior sensitivity for tumor cells with low antigen levels compared to T cells expressing monospecific and bispecific CARs." (PMID 38746248, 2024). "SLAMF7 is also critical for phagocytosis of hematopoietic tumor cells via Mac-1 integrin." (PMID 36749634, 2023). "SLAMF7 interacts with other proteins on NK cells to regulate tumor response." (PMID 37754488, 2023). "Furthermore, SLAMF7 interacts with integrin Mac-1 in macrophages and utilizes signals involving responses for tumor cell phagocytosis." (PMID 36749634, 2023). "Among potential eat-me signals, we found significant overexpression of C1Q complement components C1qa, C1qb, and C1qc, which have been shown to decorate the surface of apoptotic cells to target them for phagocytosis, and of Slamf7, which is involved in phagocytosis of hematopoietic tumor cells." (PMID 36240276, 2022). "Homotypic interaction could then occur between the SLAMF7+ tumor cells and macrophages, leading to macrophage activation and tumor phagocytosis." (PMID 35525858, 2022). "In addition, LTB, IL1A, LY9, and SLAMF7 were differentially expressed between normal and tumour tissues." (PMID 33397394, 2021). "Moreover, since the presence of the target antigen is an indispensable prerequisite for effective targeted therapy, we investigated the SLAMF7 expression on extramedullary located tumor cells before and after treatment." (PMID 33575947, 2021). "Notably, a recent study showed that SLAMF7 expression on target cells and binding to SLAMF7 on phagocytes mediated by coupling to Mac-1 are critical for the elimination of tumor cells by phagocytosis in CD47-blocking therapy." (PMID 33597728, 2021). "Many phagocytic signals are expressed on the tumor surface, including tumor-associated antigen, endoplasmic reticulum chaperone, calreticulin, and glycoprotein signal lymphocyte activation molecule family member 7 (SLAMF-7; also known as CD319)." (PMID 32765491, 2020). "In addition, many of the current popular target antigens, such as CD38 and SLAMF7 (also known as CS1 or CD319), are also found in other normal tissues, thus leading to unwanted off-tumor toxicities." (PMID 32943087, 2020). "Increased SLAMF7 expression on either tumor or immune cells may govern a macrophage’s ability to engulf hematopoietic tumor cells in response to CD47 blockade, although this result has been called into question." (PMID 35582455, 2020). "This group found that SLAMF7 serves as a key receptor promoting the phagocytosis of SLAMF7-expressing hematopoietic tumor cells by macrophages when the inhibitory SIRP-α receptor on macrophages is blocked by antibodies from detecting its ligand, CD47, on the same tumor target cells." (PMID 30455698, 2018). "Importantly, SLAMF7 expression varies across tumor types, which might impact the broader applicability of SLAMF7-targeted DNT therapy." (PMID 41168829, 2025). "The cytotoxicity promoting effects of SLAMF7-mediated co-stimulation on human CD8+ T cells highlights the potential of the SLAMF7-receptor as a therapeutic target to enhance CD8+ T cell responses leading to improved elimination of virus-infected or tumor cells." (PMID 40909279, 2025). "In these models, the phenotype of the T cells primarily was strongly affected by the lack of SLAMF7 on other cell types, such as tumor-associated macrophages or B cells, giving space for further co-stimulation or signaling/inhibition by other surface molecules." (PMID 39390117, 2025). "In addition to Slamf7 staining, Slamf6 and Nkg2d immunostaining were more spread out in ST-5-002-treated mice compared with those in mice that did not receive isoxazole treatment, which were more restricted to non-tumor regions." (PMID 39828766, 2025).
tumor (continued). "Therefore, SLAMF7-expressing T cells may be good candidates for autologous cell therapy for tumor rejection, as it potentially enhances collective cell decisions to improve CD8+ T-cell responses against weak antigens." (PMID 39390117, 2025). "From a therapeutic perspective, this spatial dependency introduces a significant challenge: SLAMF7-targeting antibodies, intended to eliminate SLAMF7-expressing tumor cells, may inadvertently bind SLAMF7 on effector CD8+ T cells, marking them for Fc-mediated clearance." (PMID 40909279, 2025). "Thus, it is tempting to speculate that combining SLAMF7 agonists with personalized vaccines could be a promising strategy to specifically amplify cytotoxic anti-tumor CD4+ T cell responses." (PMID 37965314, 2023). "Moreover, given that SLAMF7 is reported to promote the phagocytosis of tumor cells by macrophages, we also investigated whether SLAMF7 regulates bacterial phagocytosis by macrophages, which is a pivotal process for inflammation-mediated bacterial elimination." (PMID 36749634, 2023). "Moreover, agonistic engagement of SLAMF7 enhanced cytotoxicity of tumor-specific CD4+ T cells." (PMID 35237300, 2022). "In the presence of anti-SLAMF7 antibodies, the SLAMF7+ tumor cells could also be killed by ADCC." (PMID 35525858, 2022). "However, when the target antigen is not entirely MM-cell specific, such is the case with CD38 or SlamF7, increasing the affinity of (bispecific) antibodies or CAR T-cells may increase the risk of off-tumor toxicity." (PMID 32316450, 2020). "Secondly, DNT showed superior antitumor cytotoxicity against SLAMF7-expressing tumor cells because SLAMF7-SLAMF7 interaction between DNT and SLAMF7-expressing tumor cells promoted DNT cell degranulation." (PMID 41168829, 2025). "Taken together, these results demonstrate that SLAMF7 engagement during T-cell activation improves the cytotoxicity of human CD8+ T cells against viral and tumor-antigens." (PMID 40909279, 2025). "Our study demonstrates that SLAMF7 co-stimulation enhances activation, proliferation, and cytotoxic differentiation of human CD8+ T cells, including those from tumor-draining lymph nodes of HNSCC patients." (PMID 40909279, 2025). "CD8+ T cells were isolated from tumor-draining lymph nodes (TDLN) and subsequently stimulated with anti-CD3/anti-SLAMF7-coupled microspheres." (PMID 40909279, 2025). "Consequently, SLAMF7 provides an alternative co-stimulatory pathway that may trade speed for functional breadth, an attribute that could be particularly advantageous in tumor or otherwise immunocompromised microenvironments where CD80/CD86 expression is absent or functionally impaired." (PMID 40909279, 2025). "This population would enable careful assessment of on-target/off-tumour effects (NK and T cell depletion) while addressing the unmet need of BCMA-refractory disease, where SLAMF7 remains a viable target." (PMID 41228264, 2025). "SLAMF7+ DNT exhibited significantly higher expression of the proliferation marker Ki67 and the anti-apoptotic marker BCL2, accompanied by a reduced apoptosis rate, confirming that SLAMF7 promotes DNT survival and tumor-infiltrating capacity." (PMID 41168829, 2025). "In a direct tumor-killing assay, SLAMF7+ DNT demonstrated significantly greater lysis of A20 cells than SLAMF7− DNT." (PMID 41168829, 2025). "Further, we found slightly more TM4SF5 and SLAMF7 in the LAMP1 immunoprecipitates prepared from tumor tissues of TM4SF5-positive patients, compared with those from non-tumor tissues (lanes 3 to 6)." (PMID 39828766, 2025). "The full‐length SLAMF7 protein and CD47 nanobody were initially designed to construct a fusion protein targeting tumor cells." (PMID 39713206, 2024). "NCD47‐SLAMF7 consists of a signaling peptide, a nanobody that can block the function of CD47, and the extracellular region of SLAMF7, which can target tumor cells and mask their CD47 molecules." (PMID 39713206, 2024).